IRAK4 (interleukin 1 receptor associated kinase 4)
Diseases named in the same sentence as IRAK4 in open-access papers (continued):
Sharing a sentence is not in itself a finding about the gene and the disease.
cancer (35 papers, 2012 to 2026). A tumor composed of atypical neoplastic, often pleomorphic cells that invade other tissues. "Inflammation, oncogenesis, and cancer cell survival are all driven, among others, by interleukin-1 receptor-associated kinase 4 (IRAK4)." (PMID 40804253, 2025). "The meeting closed with expert discussion of the emerging profile of IRAK4 inhibition in cancers and the potential for IRAK4 inhibition to improve outcomes across both solid and liquid tumors." (PMID 40634180, 2025). "Due to the significance of IRAK4 in the TLR/IL-1R signaling pathway, many inhibitors targeting IRAK4 have been developed to treat cancers and inflammatory diseases." (PMID 40771916, 2025). "New insights into the biology of IRAK4, the development of IRAK4 inhibitors, and synergies with established treatments such as chemotherapy and targeted inhibitors were discussed at the first symposium on IRAK4 in cancer." (PMID 38666914, 2024). "The clinical value of targeting IRAK gene family members, specifically IRAK1 and IRAK4, has been elucidated in several cancer types." (PMID 37108068, 2023). "IRAK4 malfunction plays an important role in the initiation of different immune-related diseases and cancers." (PMID 38138875, 2023). "For example, PROTACs targeting AR, BR, BTK, Tau, IRAK4, and other proteins have shown unprecedented clinical efficacy in cancers, neurodegenerative diseases, inflammations, and other fields." (PMID 36142231, 2022). "Although there have been previous reports aimed at the generation of IRAK4 inhibitors, the development of cancer drugs is currently of renewed interest." (PMID 36234844, 2022). "● Increased IL-1β levels are a poor prognosis marker.● Activates IRAK4 and NF-κB, supports cancer progression and chemoresistance." (PMID 36465353, 2022). "For example, IRAK1 and IRAK4 were upregulated in most types of cancer compared with their corresponding normal tissues." (PMID 35211171, 2022). "For instance, IL-1β/IRAK4 is the feedforward signal of the tumor matrix with a very high expression level in cancer development, and disrupting the tumor-stroma IL-1β/IRAK4 feedforward circuitry improves the chemotherapy in PDAC." (PMID 34067040, 2021). "In the last years, several IRAK4 inhibitors have been developed and tested for the treatment of cancer and other diseases related to IRAK overexpression." (PMID 31197259, 2020). "Recently, drugs targeting IRAK4 have been reported for the treatment of various immune diseases and cancers." (PMID 30501110, 2018). "Both MyD88 and IRAK4 bear a huge therapeutic importance in anti-inflammatory and anti-cancer drug development." (PMID 27845762, 2016). "At the 3rd Annual IRAK4 in Cancer Symposium, experts discussed the role of IRAK4 in cancer biology, the potential for synergism between IRAK4 inhibition and other treatments to overcome resistance, and how IRAK4 inhibition may improve clinical outcomes." (PMID 40634180, 2025). "However, the design of potent and selective IRAK4 inhibitors for the treatment of cancer is still required." (PMID 36234844, 2022). "We developed an IRAK4 inhibitor that could be used in the treatment of inflammatory diseases and cancers." (PMID 30501110, 2018). "Another important function of both the exo-Hsp70 and of the endo-Hsp70 released from cancer cells may be the stimulation of MyD88/IRAK4-dependent pathway." (PMID 24797019, 2014). "TLR signaling pathways were abundantly accumulated in Mac_C2, such as MyD88 deficiency (TLR2/4), IRAK4 deficiency (TLR2/4), regulation of TLR by endogenous ligand, and disease associated with the TLR signaling cascade, which were related to the inflammatory mechanisms of in cancers." (PMID 38918785, 2024). "Interleukin-1-receptor-associated kinase 4 (IRAK4) possesses a crucial function in the toll-like receptor (TLR) signaling pathway, and the dysfunction of this molecule could lead to various infectious and immune-related diseases in addition to cancers." (PMID 38138875, 2023).
cancer (continued). "Also, IRAK2, IRAK3, and IRAK4 were higher expressed in the C6 subtype in pan-cancer." (PMID 35211171, 2022). "Cancer metastasis signaling was linked with JAK kinase, Wnt family member 9A (WNT9A), IL6, and prostaglandin-endoperoxide synthase 2 (PTGS2); whereas interleukin 1 receptor associated kinase 4 (IRAK4), and histone h3 were associated with p38MAKP signaling pathway." (PMID 30972102, 2019). "First, in terms of immune function, variations related to the nuclear factor kappa B (NF-κB) signaling pathway (NLRP12, TNIP2, IRAK4) and the autophagy process (TECPR1, ATG2A, SOGA1, TOM1) were identified in both carcinoma and sarcoma tumor groups." (PMID 40446009, 2025). "IRAK2 and IRAK4 were moderately expressed, and IRAK3 expression was the relatively lowest in pan-cancer." (PMID 35211171, 2022). "It participated in the IRAK4/IRAK1/AP-1/AKR1B10 signaling pathway and AUF1-mediated post-transcriptional regulation of AKR1B10 expression to regulate cancer stemness and drug resistance in HCC." (PMID 36246599, 2022). "Many cancers that show elevated levels of IRAK1 and IRAK4 are resistant to chemotherapy, which highlights the role of IRAK in the development of drug resistance." (PMID 32489949, 2019). "This is especially true given that many cancers exhibit increased protein levels of IRAK-1 and IRAK-4 and are resistant to chemotherapy." (PMID 25452754, 2014). "Cancer cell growth, migration, tumourigenesis and chemoresistance can all be impacted by targeting the proteins involved in the IRAK2 pathway, including IRAK1 and IRAK4." (PMID 36768848, 2023). "A number of efforts have been made to develop IRAK4 and IRAK1 inhibitors aimed at cancer treatment." (PMID 27845762, 2016). "Our working hypothesis is that in cancers with reduced levels of IRAK-M but elevated levels of IRAK-1, -2, and/or -4 will show increased IRAK-4 signaling and consequently elevated levels of inflammatory molecules." (PMID 25452754, 2014). "Data regarding the specific role of IRAK-4 in cancer have not been fully investigated, and its potential role in cancer progression is just now beginning to emerge." (PMID 25452754, 2014). "However, carcinoma samples with MMP-11 positive MICs showed a more important increase in the mRNA level of 19 factors: IL-1, −5, −6, −8, −17 and −18, ADAM-8, −10, −15, and −23, ADAMTS-1, −2, and −15, IFNβ, MMP-1, as well as mediators related to inflammation (CCL-3, IRAK-4, MyD88 and NFκB)." (PMID 23145063, 2012).
tumor (35 papers, 2012 to 2026). "In pancreatic ductal adenocarcinoma, constitutive NF-kB activity in both CAFs and tumor cells is sustained by a positive mutual loop involving secreted IL-1β and the cognate receptor IL-1 receptor–associated kinase 4 (IRAK4), expressed on both cell types." (PMID 30927908, 2019). "Regarding different OC cell lines (OVCAR3, SKOV3, A2780), the TLR4 activation induced IL-1 receptor-associated kinase (IRAK)-4 and NF-kB signaling, and c-Jun, IL-6 and IL-8 production, all of which related to tumor chemoresistance." (PMID 29343281, 2018). "IRAK4 knockdown significantly prolonged survival, reduced tumor cell adhesion, downregulated E-cadherin and Wnt4, and induced S-phase/mitotic arrest." (PMID 42146415, 2026). "In preclinical studies, combining the IRAK4 inhibitor AS2444697 or IL-1β-neutralizing antibodies with gemcitabine significantly suppressed tumor growth and reduced fibrosis, highlighting the therapeutic potential of disrupting this signaling loop." (PMID 40948749, 2025). "IRAK4 blockade and/or silencing has the potential to suppress NF‐ĸB activity, reducing fibrosis and increasing tumor chemosensitivity." (PMID 40708975, 2025). "In summary, the addition of the IRAK4 inhibitor emavusertib was beneficial to the anti-tumor activity of PI3K and BTK inhibitors and it can also overcome the acquired resistance in MZL models." (PMID 36675328, 2023). "IL-1β derived from tumour and stromal cells forms an IL-1β–IRAK4 feedforward signal that drives tumour fibrosis, chemoresistance and poor prognosis in PDAC." (PMID 35986089, 2022). "IRAK1 and IRAK4 were significantly higher expressed in LGG samples than non-tumor tissues from the Rembrandt database." (PMID 35211171, 2022). "CA-4948 is a potent interleukin-1 receptor-associated kinase 4 (IRAK-4)/FLT3 inhibitor, with potential for anti-tumor activity in AML, that is currently in the early phases of therapeutic development (NCT04278768)." (PMID 36077703, 2022). "In the context of anti-tumor T cell response, it is critical to carefully evaluate the role of IRAK4 in initial MHC-restricted T cell activation." (PMID 32961746, 2020). "In PDAC mouse models, administration of either IL-1β-neutralizing antibodies or an IRAK4 inhibitor potentiates the effect of gemcitabine in suppressing tumor growth and fibrosis." (PMID 30927908, 2019). "Knockdown of TLR8, MyD88, and IRAK4 in tumor cells significantly blocked the Poly-G3-mediated reversal of tumor-induced CD4+ T-cell senescence." (PMID 25231413, 2014). "Of all the IRAK family members, IRAK-4 was the most frequently expressed (at the medium to high range) and found on the highest percentage of tumor samples." (PMID 25452754, 2014). "Future studies will also address downstream effects of TLR3 and IRAK4 alterations on immune/inflammatory responses and tumor behavior using in vitro and in vivo models." (PMID 24194738, 2013). "High expression of TLR4 in HNSCC tumor cells in response to inflammatory stimuli has been found to be associated with IRAK4 up-regulation, AKT phosphorylation, NFκB activation and the increased proliferation of tumor cells." (PMID 24302991, 2013). "Furthermore, the role of IRAK4 in tumor growth and progression and the mode of action for IRAK4 inhibitors are still unclear." (PMID 37261210, 2023). "Additionally, it was reported that cases with melanin cell tumors experienced an elevated state of IRAK4 phosphorylation, where IRAK4 knockdown resulted in tumor growth inhibition." (PMID 38138875, 2023). "On the other hand, because chronic T cell receptor engagement is a potential mechanism that drives T cell exhaustion, a universal phenomenon in PDAC, targeting IRAK4 may be a strategy to revitalize anti-tumor T cells." (PMID 32961746, 2020). "Notably, IRAK4 inhibitors markedly reduce tumor fibrosis and synergize with gemcitabine, leading to significantly better tumor control." (PMID 32961746, 2020).
tumor (continued). "To confirm whether the results of cell culture reflected in vivo conditions, we measured TLR5, IRAK-1, and IRAK-4 gene expression in tumor tissue induced by MKN45cl85 and 85As2 cells." (PMID 30410674, 2018). "Moreover, silencing the gene expression of IRAK-4 by shRNA or the application of small molecule inhibitors can induce the proliferation of tumor cells in patients with T-acute lymphoblastic leukemia, suggesting that the signaling mediated by IRAK-4 is an important factor in disease progression." (PMID 40165954, 2025). "Importantly, the discovery of novel strategies, such as PROTACs to target IRAK4, could not only support the understanding of IRAK4 biology but could also lead to the development of new therapeutic agents to treat inflammatory and neoplastic diseases." (PMID 35702041, 2022). "In addition, tumor cells promote the immune escape of tumor cells by inhibiting IRAK4 signaling." (PMID 34863246, 2021). "IRAK4 is a protein kinase downstream of the Toll-like receptor signaling (TLR), a driver pathway of secondary tumor° resistance in both hematological and solid tumor malignancies." (PMID 36675328, 2023). "IRAK4 is a protein kinase downstream the Toll-like receptor signaling (TLR), a known driver of secondary tumor resistance in both hematological and solid tumor malignancies." (PMID 36675328, 2023). "In addition to augmenting the amounts of inflammatory factors, the lack of IRAK-M might further sustain IRAK-4 signaling and perpetuate a chronically inflamed tumor environment; chronic inflammation is a hallmark of tumorigenesis and tumor progression." (PMID 25452754, 2014). "MCF7, PC3, and M628 tumor cells were transfected with lenti-shRNAs specific for TLR8, MyD88, or IRAK4 molecules, or control lenti-shRNA, and then their ability to induce T-cell senescence in the presence of Poly-G3 was determined." (PMID 25231413, 2014). "RON directly interacts with IRAK4 to inhibit its pro-inflammatory effects in the TLR signaling pathway which suppresses type I interferon (IFN-I) signaling and thereby prevents activation of the anti-tumor response by innate immune cells." (PMID 40282397, 2025). "In a mouse xenograft model of ABC DLBCL, ND-2158 (an IRAK-4 inhibitor) decreased tumor growth without excess toxicity and significantly reduced phosphorylation of IRAK-4 (at Thr-345/Ser-346) within the tumors." (PMID 37954584, 2023). "Therefore, a combinatorial approach, targeting IRAK4 and IRAK1, would be a promising endeavor to reduce tumor progression in patients." (PMID 27845762, 2016). "For instance, IRAK4 rs4251545 was associated with a 2.56-fold increase in invasive disease (OR = 2.56; 95% CI = 1.1–5.91); whereas, inheritance of the IRAK2 rs242724 minor alleles were linked to non-aggressive disease (i.e., tumor size <2 cm, ER + /PR + /Her-2 neu+ status)." (PMID 24194738, 2013).
bacterial infections (32 papers, 2007 to 2025). "Irak4 plays a crucial function in the innate immune system, since its deficiency results in bacterial infections." (PMID 40576660, 2025). "This phenotype was also observed in MyD88- and IRAK-4–deficient patients with pyogenic bacterial infections." (PMID 36880831, 2023). "This was consistent with the phenotype of IRAK4 null humans, who, in infancy and early childhood, have a susceptibility to select bacterial infections that resolve once they reach adulthood." (PMID 37957373, 2023). "Inherited defects in both MyD88 and IRAK4 have been described, with loss of either factor leading to a similar phenotype involving a predilection for severe bacterial infections in early childhood." (PMID 34199501, 2021). "In most patients with IRAK4 deficiency, the first bacterial infection occurs before the age of 2 years." (PMID 33083971, 2021). "The initial infectious phenotypes of the majority of the patients with IRAK4 deficiency were severe bacterial infections, such as S. pneumoniae, S. aureus, and rarely P. aeruginosa and Shigella sonnei." (PMID 33083971, 2021). "Deficiencies in both MyD88 and IRAK-4 are characterized by recurrent, severe pyogenic bacterial infections involving Streptococcus pneumoniae, Staphylococcus aureus and Pseudomonas aeruginosa." (PMID 34199501, 2021). "There is a reduced susceptibility to bacterial infections when children with IRAK4 deficiency reach school age." (PMID 32532880, 2020). "Patients with IRAK4 deficiency are at risk of potentially fatal bacterial infections in infancy and childhood." (PMID 32532880, 2020). "Generally, IRAK4 deficiency is caused by homozygous or compound heterozygous IRAK4 deficiency, resulting in predisposition to recurrent invasive pyogenic bacterial infection in children." (PMID 32047491, 2019). "While the impact of TLR8 in bacterial infections in vivo still is unclear, we find these new data interesting in the context of human MyD88- and IRAK-4 deficiency, where signaling by most TLRs and IL-1Rs is lost." (PMID 31214180, 2019). "Humans with genetic defects in the central TLR/IL-1R signaling adaptors MyD88- or IRAK-4 have increased susceptibility to pyogenic bacterial infections, but only during infancy and early childhood." (PMID 31214180, 2019). "It was reported that severe invasive bacterial infections occur less frequently with age in IRAK4 deficiency." (PMID 26825884, 2016). "The clinical courses of invasive bacterial infections were often rapidly progressive despite the early, appropriate antibiotic treatment in IRAK4 deficiency patients." (PMID 26825884, 2016). "Mice deficient in Irak4 expression are more susceptible to viral and bacterial infections, and Irak4 has previously been associated with gut microbiota composition in a subset of BxD RI strains." (PMID 26260972, 2015). "Several distinct mutations in IRAK-4 have been described in humans, with loss of function associated with dramatic and recurrent bacterial infections, as well as poor inflammatory response." (PMID 21738793, 2011). "In humans, mutations resulting in IRAK-4 deficiency have been linked to susceptibility to bacterial infections, especially recurrent pyogenic bacterial infections." (PMID 19689377, 2009). "Bacterial infections involving the orofacial region such as maxillary sinusitis, necrotizing palate infection, cellulitis, and periodontal diseases have been reported in some patients with IRAK-4 and MyD88 deficiencies." (PMID 32625202, 2020). "Besides, a similar improvement with age has been reported in children with impairment of TLR signaling (IRAK-4 and Myd88 deficiencies), in whom bacterial infections become rarer with age." (PMID 32457756, 2020). "However, although IRAK4-deficient mice display broad susceptibility to viral and bacterial infections, IRAK4-deficient human patients exhibit a narrow infectious phenotype, limited primarily to pyogenic bacterial infections at an early age." (PMID 24690905, 2014).
bacterial infections (continued). "However, the IRAK4-deficient patients might carry a high bacterial burden even at the onset of invasive bacterial infection due to the low host innate immune response, which might cause severe manifestations rapidly thereafter." (PMID 26825884, 2016). "Interleukin 1 receptor associated kinase 4 (IRAK4) plays a critical role in innate immune signaling by TLR, and loss of IRAK4 activity in mice and humans increases susceptibility to bacterial infections and causes defects in TLR and IL1 ligand sensing." (PMID 36769749, 2023). "It is noteworthy that miR-302b suppressed the inflammatory response to bacterial infection by targeting IRAK4, an upstream protein required for the activation and nuclear translocation of NF-κB by activating IKKβ/IκBα." (PMID 34409030, 2021). "IRAK4 deficiency in humans impairs TLR innate immunity and causes increased susceptibility to bacterial infections including Staphylococcus aureus and Streptococcus pneumoniae." (PMID 33659224, 2020). "IRAK4 is an important upstream molecule of the NF-κB signaling pathway and has been shown to regulate proinflammatory gene expression in a bacterial infection model." (PMID 29482609, 2018). "Furthermore, the inhibition of Irak4 in both mice and humans resulted in significant pyogenic bacterial infections." (PMID 40576660, 2025). "In humans, bi-allelic mutations in IRAK4 result in IRAK-4 deficiency and increased susceptibility to pyogenic bacterial infections, but autoinflammation has never been described." (PMID 37744344, 2023). "IRAK-4 (MIM 607676) and MyD88 (MIM 612260) deficiencies, which are phenocopies in term of clinical and immunological abnormalities, are characterized by a selective predisposition to pyogenic bacterial infections." (PMID 32625202, 2020). "In addition, it has been established that IRAK4 deficiency is correlated with the compromise of toll-like receptor (TLR)/IL-1R-mediated immunity, resulting in heightened vulnerability to recurring bacterial infections that pose a significant risk to one’s life." (PMID 38138875, 2023). "Delayed separation of the umbilical cord may be the only sign for the early diagnosis of IRAK4 deficiency before the patients have highly invasive bacterial infections, in cases where they have no family history." (PMID 26825884, 2016).